CXCL9 (C-X-C motif chemokine ligand 9)
Diseases named in the same sentence as CXCL9 in open-access papers (continued):
Sharing a sentence is not in itself a finding about the gene and the disease.
tumor (continued). "While DOX administration in tumor-free mice did not result in significant changes in the expression of inflammatory markers in the heart, DOX administration significantly abrogated the tumor-induced upregulation of IL-1β, Mcp-1, Cxcl9, and Cxcl10." (PMID 34445729, 2021). "Reduced tumor endothelial FasL expression and increased plasma CXCL9 were positively correlated with increased TILs, further augmenting Th1-polarizing responses." (PMID 33723260, 2021). "Pre-clinical modeling has shown that tumor-associated eosinophils express chemokines, such as CCL5, CXCL9, and CXCL10, which promote recruitment of tumor reactive CD8+ T cells into the tumor microenvironment." (PMID 34732251, 2021). "In the large majority of tumor types, Il12b, Ifng, Ccl4, Ccl5, Cxcl9, and Cxcl10 showed a significant positive correlation with infiltration of M1 macrophages, with Ccl3 displaying a lesser overall correlation." (PMID 34446712, 2021). "IFN-γ is important for T cell, natural killer (NK) cell, and NKT cell trafficking into tumours through the induction of chemokines such as CXCL9, CXCL10, and CXCL11." (PMID 33809369, 2021). "Particularly, we found that in tumors, the expression of CXCL9 negatively correlated with tumor stage, nodal and distant metastases, and Dukes’ stage, and predictive of favorable clinical outcome." (PMID 34539647, 2021). "Recently, the elevated intra-tumoral expression of CXCL9, an IFN-γ inducible chemokine, was associated with a higher number of tumor-infiltrating NK cells, leading to favorable postoperative survival in patients with ICC." (PMID 34062821, 2021). "Heightened dual expression of the ligands for CCR5 and CXCR3 (CCL5 and CXCL9, respectively) positively correlates with the amount of tumor CD8a transcripts and patient survival in cancers of the ovary, breast, lung, colon, as well as melanoma." (PMID 34354714, 2021). "Cytokine profiling on tumor protein extracts showed a substantial increase in the expression of IL-1α and β, CXCL9 and CXCL10 in pre-terminal gal-9-KO tumors by comparison with WT and aggressive gal-9-KO tumors." (PMID 33664349, 2021). "Recently, it has been proposed that tumour cells can reduce CXCL9/CXCL10 gradients by secreting galectin-3, a lectin that blocks IFN-γ diffusion." (PMID 33809369, 2021). "In tumor, the expression level of chemokine CXCL9 and CXCL11 was significantly decreased in advanced stage CRC patients (stages IV, n = 11; p = 0.02 and p = 0.045) compared to those in early stages (stages I, II and III, n = 18)." (PMID 34539647, 2021). "Mettl3- or Mettl14-deficient tumors increased cytotoxic tumor-infiltrating CD8+ T cells and elevated secretion of IFN-c, Cxcl9, and Cxcl10 in tumor microenvironment in vivo." (PMID 34804948, 2021). "A member of the chemokine family, namely CXCL9, recruits leukocytes to sites of inflammation and plays a critical role in tumor progression." (PMID 34143198, 2021). "It is important to highlight that, in the tumor microenvironment, CXCL9-10-11 chemokines are secreted mainly by endothelial cells, fibroblasts, and cancer cells in response to IFN-γ, which are synergistically increased by TNF." (PMID 34335758, 2021). "In tumor tissues, T cell infiltration requires CCL5 derived from tumor cells and is amplified by CXCL9 secreted by myeloid cells induced by interferon-g." (PMID 34367971, 2021). "Strikingly, a large proportion of the IFNγ signature genes were upregulated by SHP2 inhibition specifically in tumor cells in co-culture, including cytokines (CXCL9, CXCL10, CXCL11 and CCL5) and antigen presenting machinery (HLA-A, HLA-B and B2M)." (PMID 33446805, 2021). "The results showed that NAPSB and CXCL9 were upregulated in PDAC tumor tissues with statistical significance." (PMID 34367961, 2021). "In the tumor, these cells are an important source of CXCL9 and CXCL10, which allow for the infiltration of both naïve and pre-activated T cells." (PMID 33418996, 2021).
tumor (continued). "Vaccination enhanced the expression of CCR5+ IFN-γ+ and CXCR3+IFN-γ+ on CD8+ T cells, which led to a significant increase in CCL5 and CXCL9/10 secretion from irradiated tumor cells." (PMID 33469123, 2021). "PBAF-deficient tumor cells efficiently responded to IFN-γ by enhancing chemokines, including CXCL9 and CXCL10, which led to the accumulation of effector T cells." (PMID 34827646, 2021). "For example, CXCR3 and its ligand CXCL9 were critical for a productive CD8+ T cell response in tumor-bearing mice treated with anti-PD-1, indicating that the CXCR3 chemokine system was an indicator of the clinical sensitivity to anti-PD-1 mAb." (PMID 34692696, 2021). "Raised levels of CXCL9 correlated with higher amounts of tumor-infiltrating natural killer (NK) cells and longer postoperative survival." (PMID 33815462, 2021). "As such, CXCL9/10/11 ligands can create a more angiostatic, immunosuppressive environment, but on the other hand they can also contribute to tumor aggressiveness." (PMID 34503058, 2021). "Recently, expression of the proinflammatory cytokines CXCL9 and CXCL10 by tumor-associated macrophages has been shown to be essential for tumor response to anti-PD-L1 therapy." (PMID 34663877, 2021). "To investigate its origin in the tumor area, we stained Cxcl9 in foci of the liver at 4 weeks after injection of sgCul3 and demonstrated its expression in stromal cells." (PMID 34803491, 2021). "JMJD3 also regulates tumor immunity in CRC by enabling the transcription of the Th-1 type chemokine (CXCL9 and CXCL10), and treating the primary cells of CRC with GSK-J4 leads to a reduction in the chemokine level." (PMID 33478063, 2021). "M2 type macrophages closely resemble tumor-associated macrophages (TAMs) and are characterized by increased expression of IFN-γ, CCL2, CCL5, CXCL16, CXCL10, CXCL9, TNF-α, MMP9 and IL-10, arginase-1, and peroxisome proliferator-activated receptor-γ (PPAR-γ)." (PMID 33925575, 2021). "Their results indicate that tumor infiltrating CD103+ DCs played an important role in T-cell trafficking by producing C-X-C motif chemokine ligand 9/10 (CXCL9/10)." (PMID 33608497, 2021). "More specifically, CXCL9 has been reported to predominantly mediate lymphocyte infiltration to tumor sites and suppression of tumor growth." (PMID 33117369, 2020). "The fold changes of CCL5 and CXCL9 were more than 2.5-fold higher in tumor tissues than the levels in normal tissues." (PMID 32081834, 2020). "In NSCLC, a study observed an upregulation of CXCL9/CCR7 in tumor tissue, especially in patients with metastasis to lymph nodes." (PMID 32974144, 2020). "The transcriptional profiling of the tumor models used in this study revealed increased levels of the chemokines Cxcl9 and Cxcl10 in tumors from Aire−/− mice." (PMID 32641748, 2020). "CXCL9/10 was associated with change of immune cell pattern in the tumour microenvironment, and supplementation of CXCL9 in the orthotopic murine PAAD model promoted tumour progression." (PMID 31913856, 2020). "The protective role of CXCL9 was confirmed in a mouse model of iCCA, in which CXCL9 knockdown led to greater tumor masses, affecting NK cell recruitment into tumor areas." (PMID 32784743, 2020). "This was reliant on PTPN2 deficiency driving the IFNγ‐induced and STAT‐1‐mediated expression of antigen‐presentation pathway genes and T‐cell chemoattractants, such as Cxcl9 in tumour cells." (PMID 31803974, 2020). "The expression of CD3D, CD3G, CXCL9, and IRF1 were significantly associated with tumor stage and distant metastasis." (PMID 32925784, 2020). "The activated T cells infiltrate tumors through chemokine CXCL9-mediated migration to kill the tumor cells." (PMID 32795913, 2020). "Treatment of tumour-bearing mice with galectin antagonists normalised CXCL9 gradients, improving influx of CD8+ T-lymphocytes specific for tumour antigen." (PMID 33187209, 2020).
tumor (continued). "Cxcl9 and Cxcl10 have been shown to play significant roles in recruiting Cxcr3+ T cells into the tumor and high levels correlate with improved patient survival." (PMID 32641748, 2020). "It has been recently shown that innate immune sensing of tumors occurs through DC activation and regulation of tumor lymphocyte infiltration via production of CXCL9 and CXCL10." (PMID 32817121, 2020). "Overall, these data support a mechanism of hetIL-15 action in which lymphocyte trafficking to the tumor is controlled by a gradient of the chemokines CXCL9 and CXCL10." (PMID 32461349, 2020). "Recent literature has indicated an important role of the chemokine CXCL9 on the tumor microenvironment, which led us to examine the potential role of this protein in our model." (PMID 33028251, 2020). "We suggest that CXCL10 and possibly CXCL9 differ from other chemokines by their ability to restrain tumor growth and enhance anti-tumor immunity." (PMID 32547545, 2020). "CXCl‐9, the chemokine that mediates lymphocytic infiltration to the focal sites and suppresses tumor growth, also showed a trend toward upregulated expression (10.1‐fold, P = 0.09)." (PMID 32797726, 2020). "Histological analysis showed that the tumour tissue in CXCL9-treated mice seemed more aggressive and active." (PMID 31913856, 2020). "In a similar manner as with CXCL9, we observed that tumor purity was low for all these genes (l and n respectively, first column)." (PMID 32796628, 2020). "In the of context adoptive cell therapy (ACT), efficacy required cDCs capable of CXCL9/CXCL10 production in order to drive tumor infiltration by the transferred T cells." (PMID 32508825, 2020). "Analyses from adjacent normal and GC samples confirmed that immune-related status was passive in the tumor microenvironment compared to normal tissues, as reflected by scarce expression of chemokines CXCL9, CXCL10, and CCL2, leading to IFN-γ restriction." (PMID 31903134, 2020). "CXCL9 has been identified as a tumor suppressor, because in 70 iCCA resection specimens high levels of CXCL9 were associated to a favorable postoperative survival." (PMID 32784743, 2020). "In general, there was a tendency for higher CXCL9/10 levels within tgCD4+ T cell-containing settings in all analyzed supernatants, hinting to both possible antitumor and tumor escape mechanisms mediated by the CXCL9/10-CXCR3 axis." (PMID 32610710, 2020). "In tumorigenesis, most studies emphasized on the relationship of CXCL9/CCR7 with tumor angiogenesis and metastasis." (PMID 32974144, 2020). "The reduced expression of anti-tumour cytokines in CXCL9-treated mice was further proven by the observation that serum level of TNFα, IL2, and IFNγ in CXCL9-treated mice was remarkably suppressed." (PMID 31913856, 2020). "The main mechanism of CXCL9 in regulating immune activity is to facilitate chemotactic recruitment of tumor infiltrating lymphocytes (TILs)." (PMID 32974144, 2020). "Inhibition of STAT3 recovered the CXCL9-inhibited proliferation, activation, and secretion of anti-tumour cytokines of CD8+ T cells." (PMID 31913856, 2020). "DCs can also secrete chemokines such as CCL2/3/4, CCL17, CCL19/21, and CXCL9/10/11 to recruit T cells and other cell subsets into the tumor sites." (PMID 33505304, 2020). "In this case, CXCR3+ tumor-specific T cells accumulate into tumors through interaction with CXCR3 ligands (CXCL9, CXCL10, and CXCL11)." (PMID 32292786, 2020). "It has been reported that the tumor production of CXCL9 and CXCL10 was repressed by enhancement of H3K27me3 and DNMT1-mediated DNA methylation." (PMID 33031059, 2020). "The BCG exposure of established BCa cell lines devoid of any tumor microenvironment reduced CXCL9 mRNA in vitro." (PMID 33003392, 2020). "The mechanism by which this occurs includes polarization of macrophages to a more M1-like state, release of anti-tumor, pro-inflammatory cytokines such as CXCL9, and a resultant influx of cytotoxic T cells to promote a “hot” tumor microenvironment." (PMID 33028251, 2020).
tumor (continued). "In stark contrast, CXCL9 is reported to suppress tumours by regulating immune cell migration, differentiation, and activation." (PMID 32181755, 2020). "Such a role of the CXCR3 chemokine system is consistent with tumor studies in which vigorous anti-tumor activities of CD8+ T cell response by the PD-1 blockade accompanies CXCL9/10 upregulation." (PMID 33584713, 2020). "As we observed a significant reduction of CD8+ cytotoxic T cells after CXCL9 treatment, we performed adoptive transfer of CD8+ cytotoxic T cells in CXCL9-treated mice to observe if the tumour-promoting action of CXCL9 was associated with the population." (PMID 31913856, 2020). "Cytotoxic T-cells are anticipated to migrate into areas of foreign/tumor antigens in response to chemokines, such as CxCL-9." (PMID 32391124, 2020). "As predicated by bioinformatics, miR-588 directly targeted CXC chemokine ligand 5 (CXCL5), CXCL9, and CXCL10, which are associated with tumor-infiltrating immune cells in GC." (PMID 33323542, 2020). "Among the chemokine ligands, CXCL1, CXCL2, CXCL6, and CXCL9 genes also displayed a higher expression in tumors with BD3 compared to low-grade tumor budding." (PMID 32719800, 2020). "Secretion of galectin-3 into the ECM by tumour cells bound the inflammatory cytokine CXCL9, effectively negating the development of chemokine gradients that would otherwise guide T-cells towards the tumour cells." (PMID 33187209, 2020). "The expression levels of CXCL9, CXCL10, CXCL11, CXCL12, and CXCL14 were associated with various tumor stages in HNSCC." (PMID 33489879, 2020). "Previous studies have correlated the accumulation of TILs in tumours with the expression of the chemokine receptor CXCR3 (receptor for CXCL9, CXCL10 and CXCL11)." (PMID 31803974, 2020). "The cytotoxic T cells expand and are attracted to the tumor site, guided by local cDC1s secreting CXCL9 and CXCL10." (PMID 33679726, 2020). "In accordance with the literature, CXCL9 or CXCL10 depletion abolished the anti-tumor efficacy of combined therapy." (PMID 33167311, 2020). "CXCL9 and 10 are expressed by tumor cells and tumor-infiltrating myeloid cells, and their receptor CXCR3 is restricted to T lymphocytes." (PMID 31775909, 2019). "Combined with our new finding that IL-17 inhibits T cell infiltration through the downregulation of CXCL9/10, it is now clear that IL-17 skews tumor immune environment towards an innate cell-dominant, tumor-promoting inflammation." (PMID 31775909, 2019). "Tumor cDC1 production of CXCL9 and CXCL10 can recruit activated T- cells to the TME where local cDC1 re-stimulation of T-cells support anti-tumor activity." (PMID 31402908, 2019). "The blockade of LIF releases the epigenetic silencing of CXCL9 triggering CD8+ T cell tumor infiltration." (PMID 31186412, 2019). "Taken together, our data show that IL-17 signals to tumor cells to downregulate the production of chemokines CXCL9/10, which are required for attracting CD8+ CTLs and Tregs to CRC." (PMID 31775909, 2019). "First, B cells are capable of producing chemokines, such as CXCL9, and cytokines, such as lymphotoxin, which recruit T cells to the tumor tissue and promote the formation of local lymphoid structures." (PMID 31623665, 2019). "In several of these therapeutic scenarios, intratumoral CD103+ DCs contributed to tumor immunity through production of T-cell recruiting chemokines such as CXCL9 and CXCL10." (PMID 31188899, 2019). "The Teff tumor gene expression signature (Teff tGE) is analysis of mRNA expression in tumor tissue for the following genes: CXCL9, INF-γ and PD-L1." (PMID 31003463, 2019). "To confirm that LIF regulates immune cell tumor infiltration through the repression of CXCL9 in tumors from actual cancer patients, we generated organotypic tissue cultures of GBM specimens freshly obtained from patients." (PMID 31186412, 2019).
tumor (continued). "Inhibition of CXCL9/10 signaling by IL-17 thus reduces the activity of anti-cancer immunity, and fosters stronger tumor-promoting inflammation." (PMID 31775909, 2019). "We confirmed changes in Cxcl9 by in situ hybridization looking at the tumor edge, where many infiltrating immune cells can be found, versus the middle of tumors, where it is more difficult for these cells to infiltrate." (PMID 31133614, 2019). "As expected, the blockade of CXCL9 prevented the increase of CD8+ T cell tumor infiltration in response to anti-LIF." (PMID 31186412, 2019). "A similar observation was made following injection of CXCL9 to the tumor site in a mouse RENCA model." (PMID 31216755, 2019). "This transendothelial migration of the tumor cells was diminished upon addition of anti-CXCL9 monoclonal antibody (mAb)." (PMID 31216755, 2019). "Here we show that IL-17 signals to transformed epithelial (tumor) cells to suppress the expression of CXCL9 and CXCL10 chemokines." (PMID 31775909, 2019). "Conversely, the inability of hematopoietic cells to respond to CXCL9/10 resulted in decreased tumor infiltration by CTLs and Tregs, decreased levels of IL-10 and TGF-β, and increased numbers of tumor lesions." (PMID 31775909, 2019). "On one hand, they promote immune cell recruitment necessary for tumor control (e.g., CXCL9/10/11 and CXCR3)." (PMID 30420855, 2018). "Tumour-infiltrating lymphocytes were detectable throughout the E-MpM series and paralleled the coordinated expression of the CXCL9, CXCL10, and CCL5 chemokines acting in lymphocyte recruitment." (PMID 30510965, 2018). "Gene profiling of BCC and SCC tumor tissue suggests an increase in IFN related genes including CXCL9 while immunohistochemical staining demonstrated the presence of CXCR3+ immune cells." (PMID 30320116, 2018). "Several of the chemokines produced by the tumor cells, including CXCL9 and CXCL10, are important with respect to their capacity to attract T cells." (PMID 30192802, 2018). "Sipa1−/− mesenchymal stroma cells (MSCs) show enhanced activation and directed migration to Bcr-Abl+ cells in tumor tissue and preferentially produce Cxcl9, which in turn recruits Sipa1−/− memory T cells that have markedly augmented chemotactic activity." (PMID 29500416, 2018). "The CXCL9/10/11-CXCR3 signaling pathway in tumor microenvironment mainly facilitated the chemotactic movement of CXCR3 activated immune cells to the tumor site for anti-tumor immunity." (PMID 29690901, 2018). "Increased expression of CXCL9 in M1-like TAMs promotes tumor infiltration by CD8+ T lymphocytes and NK cells." (PMID 29320562, 2018). "Several studies have also shown that CXCR3 expression on T cells, or expression of CXCL9 and CXCL10 in tumor tissue, is associated with increased TIL accumulation and a favourable clinical outcome in CRC." (PMID 29671006, 2018). "We tentatively conclude that galectin antagonists help the diffusion of IFNγ in the tumor microenvironment by releasing it from the galectin lattices, and thereby increasing CXCL9/10 expression." (PMID 28986561, 2017). "RT can also facilitate the recruitment of effector T-cells to the tumor by inducing the secretion of CXC motif chemokine ligand CXCL9, CXCL10 and CXCL16 by tumor cells." (PMID 29100279, 2017). "As a last example of IFN-inducible CXCR3 interacting chemokines as potential tumor suppressors, CXCL9 and CXCL10 were found to promote the natural antitumor immunity of the host also in gastric cancer." (PMID 29379506, 2017). "Using a similar model, a more recent preclinical study reported that administration of Lm-LLO-E7 increases the secretion of chemokine (C-X-C motif) ligand 9 (CXCL9) by TC1 tumor cells and mediated the intratumoral infiltration of CD8+ T cells." (PMID 28588899, 2017). "The increase in IL-6, IL-12, CCL2, CCL3, CCL5, CXCL9 levels would a priori predict for elevated levels of M1 type macrophages in the tumor, which independently validates our prior IHC staining findings." (PMID 29137331, 2017).